KRT7 (keratin 7)
Diseases named in the same sentence as KRT7 in open-access papers (continued):
Sharing a sentence is not in itself a finding about the gene and the disease.
KRT7 also shares sentences with these, for which no sentence is quoted: mucinous adenocarcinoma (28 papers); papillary renal cell carcinoma (14); prostate adenocarcinoma (13); colorectal (12); bladder adenocarcinoma (11); gastrointestinal tumors (11); lymph node metastasis (11); ovarian mucinous tumors (10); papillary thyroid carcinoma (10); ovarian mucinous adenocarcinoma (9); serous carcinoma (8); synovial sarcoma (8); cervical intraepithelial neoplasia (7); esophageal squamous cell carcinoma (7); intestinal type adenocarcinoma (7); renal carcinoma (7); bladder tumors (6); Cirrhosis (6); gallbladder carcinoma (6); metastatic colorectal cancer (6); rectal adenocarcinoma (6); adenoma (5); cervical adenocarcinoma (5); COVID-19 (5); kidney cancer (5); neuroendocrine carcinoma (5); oncocytic tumor (5); ovarian adenocarcinoma (5); urachal adenocarcinomas (5); adenosquamous carcinoma (4).
A further 261 diseases each share a sentence with KRT7 in 4 papers or fewer.